MTOR (mechanistic target of rapamycin kinase)
Diseases named in the same sentence as MTOR in open-access papers (continued):
Sharing a sentence is not in itself a finding about the gene and the disease.
tumor (continued). "In OSCC, ITGB2+CAFs activate the PI3K/AKT/mTOR axis via NADH oxidation during mitochondrial oxidative phosphorylation, accelerating tumor proliferation." (PMID 41430036, 2025). "For instance, in liver cancer, aberrant activation of the PI3K/PTEN/Akt/mTOR pathway upregulates matrix metalloproteinase 9 (MMP-9), contributing to tumor invasion and metastasis." (PMID 40704062, 2025). "One of the primary factors contributing to cancer cells' resistance to anti-tumor treatments is the activation of signalling pathways including NF-κB, PI3K/AkT/mTOR, JAK/STAT, MAPK, Wnt/β-Catenin and Notch signaling Pathways." (PMID 40176859, 2025). "This EBV-driven upregulation of KDM5B promotes tumor progression by repressing the tumor suppressor PLK2 through H3K4me3 demethylation, thereby activating the PI3K/AKT/mTOR pathway." (PMID 40059116, 2025). "Tumor development, survival, and the interaction between tumor cells and the bone microenvironment are significantly influenced by the PI3K/AKT/mTOR pathway." (PMID 40426987, 2025). "The RAS/mitogen-activated protein kinase (MAPK) and phosphoinositide 3-kinase (PI3K)/mammalian target of rapamycin (mTOR) pathways are frequently activated in UPS, contributing to tumor progression and poor prognosis." (PMID 41300979, 2025). "In contrast, TRIM22 is upregulated in glioblastoma, where it promotes tumor proliferation, while the upregulation of TRIM22 in osteosarcoma suppresses progression by destabilizing NRF2 and activating the ROS/AMPK/mTOR/autophagy signaling pathway." (PMID 40075566, 2025). "In summary, we report that TMEM45A promotes glycolysis and palbociclib resistance via the AKT/mTOR signaling pathway in BRCA, leading to enhanced tumor progression." (PMID 39910045, 2025). "Combining QSOX2 inhibitor Ebselen, mTOR inhibitor Rapamycin, and chemotherapy reduces ESCC stemness and induces tumor dormancy." (PMID 40433832, 2025). "Previous study has discovered that the aberrant activation of the PI3K/AKT/mTOR and MAPK signaling pathways contributes to tumor cell resistance." (PMID 41145422, 2025). "E2F1 is the most classical member of the E2F family and plays a multifaceted role in regulating tumor development by targeting various signaling pathways, including the Wnt/β-catenin pathway 34, the Notch pathway 35, and the PI3K/AKT/mTOR pathway." (PMID 39991770, 2025). "Quercetin, a flavonoid found in many fruits and vegetables, inhibits mTOR and reduces glycolysis through AMPK, inhibiting tumor proliferation and inducing apoptosis." (PMID 41050082, 2025). "Our study found that NEDD4 mediated the ubiquitination and degradation of PTEN by binding to PTEN, which activated the downstream PI3K/Akt/mTOR signaling pathway, thus promoting OXA and 5-Fu resistance in tumor cells." (PMID 39890782, 2025). "Recent advances reveal intricate crosstalk between HIF-1α, mTOR, and PI3K/Akt pathways in regulating lactylation, which is profoundly shaped by tumor microenvironmental contexts." (PMID 40755753, 2025). "As an inhibitor of the PI3K/AKT/mTOR signaling pathway, ART represents a promising therapeutic strategy that targets key mechanisms of tumor growth and survival." (PMID 40303931, 2025). "The PI3K/Akt/mTOR pathway, a central regulator of cell survival, metabolism, and therapy resistance, is frequently dysregulated in NPC, driving tumor progression and chemoradiotherapy failure." (PMID 40756984, 2025). "Previous studies have demonstrated that hornerin (HRNR)—a member of the S100 protein family—plays a role in regulating the mTOR signaling pathway and that it is a protein that promotes HCC tumor growth." (PMID 41169378, 2025). "This multitarget profile is particularly relevant in triple-positive breast cancer, where PR, ER-α, and HER2 converge on the PI3K/AKT/mTOR (PAM) pathway, a central axis of tumor growth and endocrine resistance." (PMID 40806603, 2025).
tumor (continued). "Consistent with the in vitro data, mTOR downstream p4E-BP1 was up-regulated, and cell surface IFNGR1 was down-regulated in CT26 RAC1A159V/WT tumor cells in vivo." (PMID 41160695, 2025). "This occurs through the molecular process wherein mTOR, a target downstream of phosphatidylinositol 3‐kinase (PI3K)/Akt in tumor cells, plays a role in the transcriptional regulation of HIF‐1." (PMID 40046406, 2025). "Two-drug combinations that target MAPK and PI3K/Akt signaling pathways in parallel impart synergistic inhibition of tumor growth and metastasis in mouse models of MM with Ras/MAPK and PI3K/AKT/mTOR activation." (PMID 40723239, 2025). "Among the most significantly dysregulated pathways in GBM, the PI3K/Akt/mTOR and MAPK/ERK pathways play a central role in tumor progression." (PMID 40076502, 2025). "Knockout or knockdown of CMTM4 in tumor cells resulted in inhibition of EGFR signaling, mTOR and PI3K/Akt pathways." (PMID 39948411, 2025). "Multiple Akt-mTOR inhibitors, including GDC-0349, GDC-0941, BEZ-235, PQR620 and MTI-31, have demonstrated significant anti-tumor activity in NSCLC preclinical models." (PMID 39929816, 2025). "Furthermore, in a murine model, Tim-3, an inhibitory receptor, was found to be upregulated in tumor-infiltrating LrNK cells, which could dampen the anti-tumor effect of LrNK cells by inhibiting the phosphatidylin-ositol-3-kinase (PI3K)/Akt/mammalian target of rapamycin (mTOR) signaling pathway." (PMID 39893278, 2025). "The main mechanisms by which GLP—1RAs promote tumor apoptosis encompass the cAMP—PKA—dependent pathway, the BMP4/Smad signaling pathway, the PI3K/Akt/mTOR signaling pathway, and the NF-κB signaling pathway." (PMID 40140925, 2025). "Pieces of evidence have shown that a large number of natural products were targeting PI3K/AKT/mTOR-induced autophagy, leading to diminishing tumor growth; thus, we explored the efficacy of baicalin on PI3K/Akt/mTOR signaling activation." (PMID 40427533, 2025). "The ROS accumulation can also activate the AMPK (AMP-activated protein kinase) pathway to inhibit mTOR (mammalian target of rapamycin) and activate FOXO (forkhead box O) in tumor cells, promoting metabolic reprogramming to alleviate ROS accumulation." (PMID 40847302, 2025). "In conclusion, this study identifies miRNA-195-5p as a key tumor suppressor in TNBC, functioning through the downregulation of MYB and consequential inhibition of the PI3K/AKT/mTOR signaling pathway." (PMID 41141380, 2025). "In contrast, the average tumor volumes of the [177Lu]Lu-DOTA-CCK2R-dimer, mTOR inhibitor, and combined treatment groups were significantly smaller (p < 0.05) at 302.72 ± 100.12 mm3, 197.63 ± 40.92 mm3, and 139.10 ± 39.86 mm3, respectively." (PMID 40963930, 2025). "PET imaging can reveal information about mTOR activity and the response to therapy by identifying the absorption of 18F‐fluorodeoxyglucose (FDG), a marker of tumor metabolism influenced by mTOR signaling." (PMID 40717210, 2025). "Tumour cells regulate cell size and growth and proliferation through multiple signalling pathways, such as PI3K/Akt/mTOR, Myc and Hippo pathways, which work together to regulate cell size and proliferation." (PMID 40525649, 2025). "Hyperactivation of the PI3K/AKT/mTOR axis is a common feature in CRC and contributes to both tumor progression and immune evasion." (PMID 41359051, 2025). "Rescue experiments confirmed the functional reciprocity, wherein MYB overexpression reversed the tumor-suppressive effects of miRNA-195-5p and reactivated PI3K/AKT/mTOR signaling, mirroring the clinical scenario of pathway activation during resistance." (PMID 41141380, 2025). "By targeting the PI3K/AKT/mTOR and EMT pathways as tumor suppressors, METTL14 can inhibit the progression and invasiveness of GC cells." (PMID 41312360, 2025).
tumor (continued). "miRNAs modulate the PI3K/Akt/mTOR pathway in HCC either as oncomiRs or tumor suppressor miRNAs, thereby influencing tumor progression, metastasis, and treatment responses." (PMID 40943288, 2025). "We further detected the expression of mTOR, p-mTOR, PI3K, Akt, p-Akt, PINK1, and Parkin in tumor tissues via WB." (PMID 40944197, 2025). "In mouse tumor models, M2 TAMs have been shown to preferentially express soluble GPNMB which combines with the CD44 receptor on tumor cells and promotes CSC proliferation via PI3K/AKT/mTOR or β-catenin/MAPKs/AMPK/Src signaling." (PMID 40380196, 2025). "Two-drug combinations targeting MAPK and PI3K/Akt signaling pathways in parallel impart synergistic inhibition of tumor growth and metastasis in mouse models of MM with Ras/MAPK and PI3K/AKT/mTOR activation." (PMID 40568110, 2025). "For instance, in HER2-positive GC, SMO inhibition reduced tumour growth and restored trastuzumab sensitivity by inactivating the AKT/mTOR pathway." (PMID 40426308, 2025). "In addition, FABP5 could promote tumor progression by activating PI3K/Akt/mTOR signaling." (PMID 39871325, 2025). "Previous study has shown that HBEGF promotes myocardial interstitial fibrosis via the Akt/mTOR pathway, suggesting a potential cooperative role with IGF‐1 in modulating QSOX2 expression in tumor cells through Akt/mTOR signaling." (PMID 40433832, 2025). "Multiple signal transduction pathways are involved in the proliferation, clonogenicity and migration of tumor cells via the activation of signaling pathways, including PI3K/AKT/mTOR, RAS/MAPK and Wnt/β-catenin, among others." (PMID 39781344, 2025). "In turn, mTOR activation has been shown to upregulate MMP-2 and MMP-9—downstream effectors that degrade the ECM and facilitate tumour cell invasion." (PMID 40860666, 2025). "In vivo studies further corroborated these results as gypenosides greatly inhibited tumor growth (p < 0.05), largely by promoting apoptosis through the PI3K/AKT/mTOR pathway suppression." (PMID 40717210, 2025). "These modifications result in reduced α8β1 expression, contributing to shorter survival times, alterations in tumor microenvironment, and activation of key signaling pathways such as PI3k/AKT/mTOR, which promote tumor proliferation, invasion, and metastasis." (PMID 40510035, 2025). "The regulatory effects of ginkgetin on the PI3K/Akt/mTOR signaling pathway and AMPK pathway demonstrate its potential in regulating tumor cell metabolism." (PMID 40762894, 2025). "The PI3K/Akt/mTOR signaling cascade is frequently activated by PIK3CA alterations or by PTEN inactivation and is well known to promote tumor growth, angiogenesis, and metabolic reprogramming." (PMID 41155343, 2025). "TNF‐α, while capable of inducing apoptosis via mTOR inhibition, paradoxically enhances cell survival and proliferation through NF‐κB and MAPK activation, creating a tumor‐promoting inflammatory state." (PMID 40387523, 2025). "By modulating the expression or activity of autophagy-related genes and interacting with critical signaling pathways—such as the AMPK/mTOR, PI3K/AKT, and Beclin1 pathways—lncRNAs orchestrate the dynamic balance between autophagy and tumor cell fate." (PMID 40789840, 2025). "The mTOR signaling pathway is essential in tumor development through its regulation of cell proliferation, metabolism, and metastasis, and through its hyperactivation within the PI3K/Akt/mTOR cascade." (PMID 40500799, 2025). "Previous studies have shown that the TSC/mTOR and RTK pathways play critical roles in regulating tumor stemness and angiogenesis." (PMID 40255077, 2025). "By downregulating these tumor suppressors, the PI3K/AKT/mTOR axis drives aberrant cell cycle progression and facilitates unchecked proliferation." (PMID 40182139, 2025). "Polyphenols such as curcumin and resveratrol can target the PI3K/AKT/mTOR pathway, inhibiting AKT phosphorylation and mTOR function, thereby promoting apoptosis in tumor cells." (PMID 41301459, 2025).
tumor (continued). "This is because mTOR can activate the STAT3 pathway and together, the mTOR/STAT3 pathway promotes the development of tumours." (PMID 40407951, 2025). "FABP5 enhances tumour cell proliferation and migration via pathways including PI3K/AKT/mTOR and cAMP response element-binding protein (CREB)-mediated miR-889-5p signalling, which targets and suppresses the tumour suppressor Kruppel-like factor 9 (KLF9)." (PMID 41149452, 2025). "By decreasing mTOR activity, a negative regulator of autophagy, HK2 can enhance autophagic processes, contributing to increased tumor cell resistance to TAM therapy." (PMID 40303296, 2025). "miR-99a-5p suppresses growth, migration, and invasion by targeting mTOR in RCC and bladder cancer and FGFR3 in PCa, and inhibits tumor growth by targeting IGF1R." (PMID 40161350, 2025). "MRPL21 affected the mitochondrial OXPHOS process and modulated tumor cell proliferation, metastasis, and autophagy via PARP1 activity and the downstream PI3K/AKT/mTOR signaling pathway, thereby contributing to chemoresistance of HNSCC." (PMID 40713706, 2025). "It similarly revealed that SHC1 overexpression enriched in several tumor-related signaling pathways, including PI-3K/AKT/mTOR and EMT, and in addition, our results suggested that all 3 genes were involved in immune-associated pathways." (PMID 40953006, 2025). "NF-κB activation induces APOBEC3B mutagenesis and PD-L1 overexpression, while mTOR signaling enhances glycolysis and OXPHOS to fuel tumor growth." (PMID 40510156, 2025). "In conclusion, this study reveals that CD147-high EVs derived from GC play a critical role in modulating endothelial cell function, disrupting the vascular barrier, and promoting tumor metastasis via the VEGF/AKT/eNOS/NO and AKT/mTOR/p70S6K signaling pathways." (PMID 40541935, 2025). "Collectively, these findings suggest that shikonin can exerts its anti-tumor effects by binding to and upregulating TEK, which subsequently suppresses the AKT/mTOR signaling pathway." (PMID 40808675, 2025). "In certain subtypes, particularly those with classical differentiation, overexpression of HNF4α supports tumor progression by promoting metabolic reprogramming—notably enhancing lipogenesis and glycolysis through the SREBP-1c and mTOR pathways." (PMID 40926269, 2025). "EGFRvIII likely bypasses the proliferative inhibition caused by Olig1/2 loss through constitutive activation of downstream signaling pathways (e.g., PI3K/AKT/mTOR and MAPK/ERK), thereby providing alternative survival and proliferative signals for tumor cells." (PMID 40428395, 2025). "IGF‐1, a potent mitogen, promotes cell proliferation and survival while inhibiting apoptosis via PI3K/AKT/mammalian target of rapamycin (mTOR) and MAPK pathways, fostering tumor initiation and progression." (PMID 41267926, 2025). "LINC01554 exerts tumor-suppressive functions by promoting ubiquitin-mediated degradation of PKM2 and inhibiting AKT and mTOR phosphorylation in HCC." (PMID 41361062, 2025). "Previous studies have established that the expression of CD274/PD-L1 was associated with multiple signaling pathways, including IL-6/JAK/STAT3, PI-3K/AKT/mTOR, JAK/STAT, and WNT, which collectively influenced the tumor immune microenvironment." (PMID 40953006, 2025). "It is described as an “effective cooperating oncogene” and is closely associated with the activity of multiple signaling pathways and molecules, such as PI3K/Akt, mTOR, and MAPK, that govern the growth and survival of tumor cells." (PMID 40809015, 2025). "These inhibitors block tumor cell proliferation and survival by targeting key nodes of the PI3K/Akt pathway, including PI3K, Akt, and mTOR." (PMID 40823184, 2025).
tumor (continued). "Axl mainly functions through PI3K/AKT/mTOR, JAK/STAT, NF‐κB and RAS/RAF/MEK/ERK signalling pathways to facilitate tumour cell survival, antiapoptosis signalling, mitogenesis, migration and invasion." (PMID 39779468, 2025). "Meanwhile, some counter-regulatory mechanisms exist, such as miR-206 and miR-99b, that mediate the transition of TAMs back to an M1 state by activating NF-κB and suppressing mTOR/IRF4, enhancing CD8+ T-cell recruitment and tumor phagocytosis." (PMID 41007803, 2025). "Among these pathways, phosphatidylinositol 3-kinase (PI3K)/protein kinase B (Akt)/mammalian target of rapamycin (mTOR) signaling is frequently dysregulated in HCC and plays a central role in tumor development, angiogenesis, metastasis, and chemoresistance." (PMID 40943288, 2025). "TSRP can suppress tumor cell proliferation and migration by downregulating the activity of the PI3K/Akt/mTOR signaling pathway." (PMID 40328748, 2025). "In these clusters, gene sets related to cell proliferation and tumor initiation were enriched, including pathways such as E2F targets, G2M checkpoint, MYC targets v2, Wnt, PI3K/AKT/mTOR, Notch, TGF-β, and Hedgehog signaling." (PMID 39872221, 2025). "Given the known tumor-suppressive functions of AMPK through the inhibition of mTOR signaling and induction of energy stress responses, the negative correlation between EphA5 and pAMPK suggests that EphA5 expression may be attenuated in metabolically restrained tumor environments." (PMID 40806980, 2025). "In short, the mTOR and JAK pathways affects the activation of STAT3, which leads to tumour development and progression." (PMID 40407951, 2025). "A phase II clinical trial for HNSCC (NCT04632992) is currently underway, focusing on evaluating its early anti-tumor activity and safety in HNSCC with abnormal activation of the PI3K/Akt/mTOR pathway." (PMID 40723456, 2025). "Conversely, CBX2 knockdown inhibits tumor growth and sensitizes cells to chemotherapy by restoring PTEN activity and suppressing the AKT/mTOR pathway." (PMID 40565099, 2025). "PTEN and TSC2 act as tumor suppressors by negatively regulating AKT, a key activator of mTOR signaling." (PMID 41465847, 2025). "The tumor suppressor STK11/LKB1 activates AMPK, a central metabolic sensor that integrates energy stress signals through cross-talk with PI3K, mTOR, and MAPK pathways." (PMID 41179661, 2025). "Previous studies have identified LINC01554 as a liver-enriched tumor suppressor lncRNA that regulates glucose metabolism by promoting PKM2 degradation and inhibiting the Akt/mTOR pathway, thereby suppressing HCC progression." (PMID 41515582, 2025). "Glucose depletion leads to a series of weakening of mTOR activity, glycolytic capacity, and IFN-γ production, resulting in anti-tumor dysfunction of NK cells." (PMID 40696413, 2025). "Supplementation with valine enhanced proliferation and mTOR signaling in tumorigenic FTE cells, suggesting the potential of BCAAs as a nutrient utilized by tumor cells during omental colonization and a possible target for metastasis." (PMID 40066850, 2025). "Increased levels of G-CSF in serum from tumor-bearing mice activated the PI3K/Akt/mTOR signaling pathway and immunosuppressive functions of G-MDSCs generated in the context of a B16F10 melanoma tumor model." (PMID 40725182, 2025). "In GSEA enrichment analysis, important tumor signaling pathways including PI3K-AKT, Hippo, WNT, and mTOR were significantly downregulated in the EBV-positive group (FDR < 0.05)." (PMID 41372946, 2025). "The PI3K/AKT/mTOR pathway is also central to OSCC pathogenesis; its hyperactivation sustains tumor-cell proliferation, survival, metabolic reprogramming, and motility." (PMID 41614860, 2025). "Research has shown that the overexpression of SOCS5 promotes tumor growth and invasion through autophagy, which is mediated by the PI3K/AKT/mTOR signaling pathway." (PMID 41326907, 2025).